IFNG (interferon gamma)
Diseases named in the same sentence as IFNG in open-access papers (continued):
Sharing a sentence is not in itself a finding about the gene and the disease.
infection (continued). "A predominant Th1 immune response was observed during infection, as 6 of 11 investigated Th1 associated genes, including TNF, IFNG, and some IFNG-signaling responsive genes (SOCS1, STAT1, WARS and IRF1), were strongly up-regulated at 24 hpi and/or 48 hpi." (PMID 18811943, 2008). "We have shown that mGBPs are highly induced upon IFNγ stimulation and infection with intracellular bacteria or protozoa indicating an important role as effector molecules in host defense." (PMID 18402675, 2008). "The infected mice secreted significant amount of proinflammatory cytokines like TNFα and MCP-1 and high amount of IFNγ, IL-1 and IL-6 at 24 h post infection." (PMID 18937835, 2008). "Although only a limited physiological role was found for CD1d-restricted NKT cells during experimental VL, the activation of these cells has been shown to improve disease outcome in many infections, often via the increased production of IFNγ." (PMID 18463695, 2008). "Recently, it was shown that infection of mice with RSV results in the induction of CD8+ CTL in lungs that are characterized by a low percentage of cells secreting IFNγ, which is a direct measure of their cytolytic activity." (PMID 18816384, 2008). "The development of commercial interferon-gamma (IFN-γ) release assays (IGRA) has focussed attention on the use of host immune reactivity as a marker of infection." (PMID 18092001, 2007). "IFNγ, TNFα, and other pro-inflammatory mediators produced by these cells when responding to obligate intracellular infections are known to activate macrophages, which inhibit growth of both R. rickettsii and E. chaffeensis." (PMID 16859547, 2006). "IFNγ derived from T and NK cells has been shown to be essential, as mice with a disruption of the IFNγ signalling are unable to restrict the growth of M. tuberculosis and succumb to the infection." (PMID 16285886, 2005). "Additionally, pp65 and IE-1-specific CD8+IFNγ+ T-cell responses were significantly greater than those against gH and gL/pUL128L at the resolution of infection." (PMID 41599037, 2026). "In summary, while IFNγ and IL‐2 production from bulk T cells, as measured by Fluorospot, was maintained over time post‐infection in the complete cohort, a more detailed examination of S‐specific CD4+ T cells by ICS revealed subset and polyfunctional (3–4 cytokine) responses that declined over time." (PMID 41427434, 2025). "Additionally, these T cells potentiate IFNγ production by natural killer (NK) cells, via TNFα and interleukin (IL)-12 produced during infection." (PMID 41452934, 2025). "This correlated with increased expression of human IFNγ in the intestine after infection." (PMID 40614970, 2025). "Infection with T. gondii activates inflammatory molecules—Interferon gamma (IFN-γ), Interleukin-2 (IL-2), and Tumor necrosis factor alpha (TNF-α)—which upregulate tryptophan-2,3-dioxygenase (TDO) and indoleamine-2,3-dioxygenase (IDO) while leading to degradation of tryptophan into kynurenine." (PMID 40868805, 2025). "An adaptive response driven by T-helper 1 lymphocytes (Th1) triggers an effective immune reaction that helps manage the infection by promoting the production of proinflammatory cytokines such as interferon-gamma (IFN-γ), interleukin-2 (IL-2), and tumor necrosis factor-alpha (TNF-α)." (PMID 41310729, 2025). "Loss of IFNγ did significantly improve the formation of MPECs during PbA infection, but this did not affect long-term persistence." (PMID 40163479, 2025). "Additionally, these T cells potentiate IFNγ production by natural killer (NK) cells, likely via TNFα and interleukin (IL)-12 produced during infection." (PMID 40667022, 2025). "Ccl4 was upregulated by SFV/Luc, but reduced with SFV/IFNγ infection." (PMID 40547518, 2025). "At 4 hr post-infection, cells were treated with 200 U/ml IFNγ." (PMID 40608405, 2025). "To determine whether IL-12 or TNFα influence IFNγ production by NK cells, we treated PBMCs at the start of infection with anti-IL-12/23 p40, anti-TNFα, or both." (PMID 41452934, 2025).
infection (continued). "Moreover, infection with SFV/IFNγ and SFV/TNFα upregulated the amount of IL-6, CCL4 and CXCL11 (p < 0.05)." (PMID 40547518, 2025). "Additionally, delivering immunomodulating genes such as IFNγ or TNFα enhanced the effects of the infection." (PMID 40547518, 2025). "IFNγ is essential for activation of macrophages for intracellular killing of S. aureus but is modulated by production of IL-13 and other cytokines to prevent excess inflammation during response to infection." (PMID 39966757, 2025). "Only around 10% of the samples demonstrated detectable IFNγ responses one year post infection." (PMID 40867680, 2025). "Since IFNγ and IL-17 can cross-regulate each other and IL-17 is critical for host defense against C. auris, we hypothesized if increased IFNγ diminishes protective IL-17 response and increases fungal burden during C. auris-infection." (PMID 40294061, 2025). "At 30 h post-infection (MOI 0.5), the IFNγ-induced HLA-I expression was effectively suppressed by both B.1 and B.1.1.7 variants, reducing surface expression by 56% and 54%, respectively, compared to IFNγ-stimulated mock-treated cells." (PMID 40872797, 2025). "CD8+ T cells also produce IFNγ within hours of infection as part of their cytolytic mechanism." (PMID 40431612, 2025). "Besides the multifaceted functions of IFNγ, IL-15 produced early after infection can activate memory CD8+ T cells, upregulating the expression of NK receptors such as NKG2D." (PMID 41438743, 2025). "IFNg enhances the cellular immune response following infection and vaccination." (PMID 39936078, 2025). "With the reduced IFNγ production by TACR1 T cell cKO compared to WT mice during infection, we assessed whether T cells from these mice were able to proliferate and differentiate to Th1 or Th17 T cells." (PMID 39937862, 2025). "Second, TNF may play a larger role during Mab control in mice compared to IFNγ, which is different from infections with Mtb." (PMID 40415550, 2025). "To evaluate whether this effect extends to other infectious models, we performed experiments using intraperitoneal challenge with Candida albicans and assessed IFNγ expression on D2 post-infection." (PMID 41438743, 2025). "Moreover, infection with SFV/IFNγ specifically inhibited GM-CSF, CCL20 and CXCL5 compared to the SFV group (p < 0.0001)." (PMID 40547518, 2025). "Infection-induced increases in IFNγ-IFNγ receptor signaling are a known driver of crypt hyperplasia, as infection of IFNγ receptor-deficient mice failed to induce crypt hyperplasia." (PMID 40501768, 2025). "IL-2 stimulation induces histone acetylation at effector gene enhancers such as interferon gamma, and broader epigenetic variability, potentially shaped by factors like age, environmental exposure, or infection history, may influence NK-cell responsiveness." (PMID 40862731, 2025). "Using a closely related collection of C. neoformans sequence-type 93 isolates, mouse virulence could be mapped to single nucleotide polymorphisms in specific genes, some of which also correlated with IFNγ levels upon infection." (PMID 41440711, 2025). "We hypothesize that intrOv may be able to induce IFNγ+ILC3s in the lower genital tract to delay the infection process." (PMID 40407332, 2025). "In previous reports, BoDV1 replication was higher in mice deficient in interferon gamma, and we confirmed a role for this cytokine in BoDV1 restriction at 12 weeks post infection using mice lacking its receptor." (PMID 40344162, 2025). "This suggests that the protection conferred by PEP-R619W during MHV A59 infection may be driven, in part, by enhanced NK cell IFNγ production." (PMID 40791464, 2025). "Infection with H. pylori activates both Th1 and Th17 pathways, leading to the production of pro-inflammatory cytokines such as interferon-gamma (IFN-γ) and IL-17, which contribute to epithelial inflammation, atrophic changes, and the onset of intestinal metaplasia." (PMID 40806347, 2025).
infection (continued). "For instance, female T cells can express more CD40LG or CXCR3, both of which are X-linked, and are generally more responsive to activation, produce more effector molecules like IFNγ in response to infection, and generate more short-lived effector cells than male-derived T cells." (PMID 40143355, 2025). "Prior to the routine use of antifungal prophylaxis in CGD, a randomized placebo-controlled study showed that the addition of interferon-gamma (IFNγ) decreased serious infections by about two thirds, and so many centers use IFNγ in addition to TMP/SMX and itraconazole." (PMID 41608118, 2025). "What’s more, the cytokines IFNγ and IL-21 were both strongly induced, which could indicate that infection stimulates double producers or that follicular helper T (TFH) cells were also released from the spleen." (PMID 40214640, 2025). "We find that interferons have a modest impact on LDV replication, with interferon-alpha blunting LDV viremia in the acute phase of the infection and interferon-gamma reducing LDV viral loads in the chronic phase of infection, but only when paired with an intact interferon-alpha response." (PMID 40338081, 2025). "Supporting our findings about the relationship between IL-6 and Th-1 cytokines, several studies indicate that IL-6 interferes in the response of MΦs infected with mycobacteria to produce IFNγ, thus limiting the Th1 response’s ability to eradicate the infection." (PMID 41189022, 2025). "Infection increased both the percentage of CD3+ Vγ9+ lymphocytes producing IFNγ and their iMFI." (PMID 40667022, 2025). "Therefore, to test this assumption, we isolated M. bovis BCG from macrophages at 24 h post-infection, cultured in the culture broth, treated with IFNγ, and analyzed its growth." (PMID 39222120, 2024). "TB2 detects CD8-mediated interferon gamma response, a potential marker of recent infection." (PMID 38768253, 2024). "Findings from proteomic and TEM analyses suggest that interaction with IFNγ may impact mycobacterial growth and infection." (PMID 39222120, 2024). "IFNγ produced by liver ILC1s contributes to the control of hepatic MCMV infection under conditions in which the liver is directly infected via hydrodynamic infection." (PMID 38684766, 2024). "Infection with either parasite strain led to rapid death of IFNγ-/- mice." (PMID 38857298, 2024). "Interferon gamma release assays demonstrated successful infection of all calves, while examination of humoral responses using a commercial ELISA identified a low number of infected animals at weeks 4–8 after infection." (PMID 39195811, 2024). "Notably, we observed an elevated IFNγ response in female mice in all groups compared to their respective male counterparts during infection." (PMID 38999932, 2024). "Furthermore, we controlled for priming effects by interferon-gamma (IFNγ) treatment before infection and included an LPS control, allowing to identify effects caused by bacterial activation of Toll-like receptor 4 (TLR4)." (PMID 39366977, 2024). "Additionally, inflammatory markers such as IL18 and IFNG demonstrate differential expression, with increased activity in certain infection states, reflecting their role in modulating inflammation in response to ROS." (PMID 39770656, 2024). "Interestingly, Lgals3−/− mice had higher Th1 responses with increased IL-12p40 and IFNγ detected in the sera, as well as from cultured splenocytes after infection." (PMID 39302131, 2024). "Interestingly, live/dead staining and quantification of IFNγ revealed that oHSV-D11mt infection markedly enhanced cytotoxicity and IFNγ secretion when co-cultured with PBMCs." (PMID 38853689, 2024). "Our previous work described MyD88-dependent production of IFNγ that was detected both at the site of infection and in the serum during the first few hours of N. caninum infection, but the cells producing IFNγ immediately after infection remained unknown." (PMID 39445806, 2024).
infection (continued). "Subsequently (days 1–3 post-infection), this recognition triggers the production of IFNγ, primarily by natural killer (NK) cells, innate lymphoid cells (ILCs), and γδT cells, providing sufficient stimulation to infected cells for clearing the infection and preventing dissemination." (PMID 39065071, 2024). "Together, these results suggest that a soluble protein component in N. caninum tachyzoite lysate is activating immediate IFNγ production in mouse infections, and they do so with greater potency than similar preparations from T. gondii in a manner consistent with what is observed with live parasites." (PMID 39445806, 2024). "These low levels of infection did not cause a significant inflammatory response and are comparable to the levels of IFNγ, IL1β and TNFα in un-infected tissue (Fig. 4A2c)." (PMID 38797844, 2024). "Infection-dependent decreases in transcript, protein, and phosphoprotein were rescued when de novo bacterial protein synthesis was inhibited with chloramphenicol, restoring expression of IFNγ-target genes." (PMID 39194253, 2024). "The graphical summary of the LPS-treated and control HNEpC dataset illustrated that LPS induces the stimulation of leukocytes, immune cell responses, antimicrobial reactions, neuroinflammation signaling, IFNG immune responses, neutrophil immune responses, and mammalian infections." (PMID 38561377, 2024). "Altogether, our results showed that alveolar lymphocytosis, with increased numbers of alveolar IFNG -expressing cells and CD8 + poly-cytotoxic T cells, as well as activated AM were strongly associated with protection from persistent Mtb infection in PLWH." (PMID 38352496, 2024). "NKp46+ cells (classical NK cells and ILC1s), as well as macrophages, were present in both uninfected and MCMV-infected ovaries and exhibited an activated phenotype (production of IFNγ and granzyme B by NKp46+ cells; induction of F4/80 in macrophages) following infection." (PMID 39134803, 2024). "Notably, despite the different CD8+ T-cell levels between the 6-month- and 9-month-primed mice, we observed comparable responses after booster infection, based on IFNγ responses, and IAV-specific T-cell frequencies and repertoire diversity." (PMID 38675801, 2024). "In contrast, 40 days post infection ~50% of M09 cells produced IFNγ." (PMID 38236791, 2024). "The circulating cytokine (IL-6, IFNγ, and IP-10) levels were decreased at Day 4 after infection." (PMID 38474386, 2024). "Imad and colleagues studied the cytokine profile of 96 hospitalized adult patients admitted to the Hospital for Tropical Diseases, Bangkok, Thailand, during 2015–2016, which showed the increased expression of protein interleukins (IL-4, -6, -8, -10), TNFα, and IFNγ during infection." (PMID 39200005, 2024). "After booster infection, the IFNγ–ELISpot assays often reached the upper limit of detection, due to which we might not have been able to detect potential differences between 6 m primed and 9 m primed mice." (PMID 38675801, 2024). "Overall, our study uncovered detailed contributions of innate cells to vaccine-induced protection by serving as key sources of innate IFNγ, helping in the activation of T cells after immunization, and as mediators of vaccine-induced protection against lethal Cn-H99 infection." (PMID 39324785, 2024). "This was accompanied by changes in cytokine profiles and parasite loads which were dependent on the cell type (CD4+ T, CD8+ T, NK, NKT and γδ T cells), the organ (SI, PP, MLN, SPL and liver), the time-point (day 5 and 10 post-infection) and the cytokine (IFNγ, IL-4, IL-10 and IL-13) studied." (PMID 38950025, 2024). "However, when Compound 1 was introduced during infection with ∆myr1 mutants combined with IFNγ stimulation, the infected cells displayed characteristics such as cell rounding, detachment, and the uptake of SYTOX green." (PMID 39292011, 2024).
infection (continued). "In our mouse model, the early phase of the protective immune response against B. melitensis varies according to the organs: at 120 hours post-infection, an IL-17RA-dependent (Th17) response controls the infection in the lungs and an IFNγ-dependent (Th1) response controls the infection in the spleen." (PMID 39186777, 2024). "However, an adaptive cell-mediated immune response (CMI) of the infected host controls the facultative intracellular pathogen during early infection stages with interferon gamma (IFN-γ) as key effector cytokine." (PMID 38822400, 2024). "Successful infection of all calves was demonstrated using an interferon gamma release assay." (PMID 39195811, 2024). "The combined gene expression results from the CLN, brain and spleen indicate that infection by EQ40 tachyzoites is characterized by high IFNγ expression, which together with high T-bet expression, points to a strong systemic inflammatory reaction, possibly resulting in immunopathology." (PMID 38912206, 2024). "The IFNγ gene showed significant differential expression only 7 days post-infection." (PMID 38467747, 2024). "Ferritin, an ARP, is increased in many inflammatory states, and it may serve as a biomarker for CRS, HLH in hematologic disorders, but when used as a predictor of infection, ferritin is affected by a variety of factors including IL-6, IL-10, IL-18, and IFNγ." (PMID 39559703, 2024). "However, rC1 caused remarkable liver damage, also inducing elevated AST levels and increased plasma IFNγ levels, indicating an ongoing response to infection." (PMID 38257787, 2024). "IFNγ increases in vitro infection of murine astrocytes by trypomastigote forms of T. cruzi." (PMID 38776344, 2024). "Both treatments were associated with similar proportions of IFNγ-producing CD8+ T cells in the lung digest at days 7 and 10 post-infection, but PR8-infected BMDCs significantly increased NP- and PA-specific CD8+ T cells in the BAL of pups on day 7 post-infection." (PMID 39205245, 2024). "However, very few T cells are present in the upper FRT and the numbers of IFNγ-producing T cells are unaltered in Ifne-/- mice at this time-point of infection (Fig. EV2H)." (PMID 38263527, 2024). "In addition to providing help with B cell production of antibodies, CD4+ T cells release proinflammatory effector molecules, such as IFNγ and TNFα, during infection." (PMID 38567021, 2024). "Together, the complementary effects of increased CEC and ABCA1 may reduce intracellular cholesterol levels during infection and contribute to IFNγ-independent Mtb control in RSTR." (PMID 39162406, 2024). "In pigs vaccinated with attenuated ASFV, the antigen-specific responsiveness of γδ T cells is assessed via IFNγ production, revealing an enhanced proportion of these cells producing IFNγ by 7 days post infection, an early response compared to traditional T cells and NK cells." (PMID 39591181, 2024). "By comparing the infection site at early time points following chlamydial challenge, we found that a greater abundance of innate effector populations and proinflammatory signaling, including IFNγ correlated with protection." (PMID 38826233, 2024). "IFNγ production is essential for protective Th1 priming against infections." (PMID 39324785, 2024). "Likewise, S + MBC counts and T cell response, as reflected by IFNγ release levels at 3-month after the start of vaccination, were also predictive of protection against symptomatic infection." (PMID 38689059, 2024). "The quadruple knockout ∆ist/∆gra16/∆gra24/∆gra28 also phenocopied Δmyr1 infection effect on host cell survival upon IFNγ treatment in combination with Compound 1, showing a nearly 60% infected cell death rate accumulated over 60 h of continuous time-lapse observation." (PMID 39292011, 2024). "The implication of this finding in vivo may be that conversion and encystation must happen early after infection to avoid high IFNγ conditions which favor clearance." (PMID 38912206, 2024).